LEPR (leptin receptor)
Diseases named in the same sentence as LEPR in open-access papers (continued):
Sharing a sentence is not in itself a finding about the gene and the disease.
glioma (3 papers, 2017 to 2024). A benign or malignant brain and spinal cord tumor that arises from glial cells (astrocytes, oligodendrocytes, ependymal cells). "Since inflammation and over-expression of growth factors in glioma tumors involves pro-inflammatory proteins production, including sPLA2-IIA; and these factors induce upregulation of the leptin receptor, it is conceivable that leptin has a cooperative role." (PMID 28249041, 2017). "Significant expression of the leptin receptor has been shown in CD133+ cells and knockdown of leptin receptor effectively lowered the invasiveness of stem-like cells in gliomas and confirmed that JAK/STAT3 signaling is the molecular mechanism involved in the invasion of U87 glioma cells." (PMID 30803210, 2019).
Hypoglycemia (3 papers, 2010 to 2021). A decreased concentration of glucose in the blood. "Collectively, these findings indicate that central GH action in SF1/LepR-positive neurons is relevant for recovery from hypoglycemia." (PMID 33440789, 2021). "Inactivation of GHR in LepR-expressing cells also impairs the CRR to hypoglycemia, which is in line with the high degree of co-localization between SF1 and LepR expression in the VMH." (PMID 33440789, 2021). "We speculate that an increase in fetal soluble leptin receptor, potentially leading to a decrease in leptin signaling, might have a protective role against leptin-induced hypoglycemia, while a corresponding increase in placental leptin might play a role in sustaining placental function." (PMID 32778645, 2020).
inflammatory bowel disease (3 papers, 2019 to 2021). A spectrum of small and large bowel inflammatory diseases of unknown etiology. "Previous studies have demonstrated that leptin deficiency as well as the pharmacologic blockade of the leptin receptor attenuate disease severity in mouse models of colitis, highlighting a potential role for leptin in inflammatory bowel diseases." (PMID 31822667, 2019).
lipodystrophy (3 papers, 2019 to 2024). A congenital or acquired disorder characterized by abnormal loss or redistribution of the adipose tissue in the body. "Conversely, leptin receptor antagonists reduced REE in patients with lipodystrophy." (PMID 35369060, 2022).
multiple sclerosis (3 papers, 2014 to 2023). A progressive autoimmune disorder affecting the central nervous system resulting in demyelination. "For example, elevated leptin levels correlate with a reduced number of CD4+CD25+ regulatory T cells in patients with relapsing-remitting multiple sclerosis, and treatment of mice with a soluble leptin receptor (LepR) fusion protein ameliorates disease in an experimental model of multiple sclerosis." (PMID 38031726, 2023).
nonalcoholic fatty liver disease (3 papers, 2019 to 2025). "Kefir significantly improved the body weight, energy expenditure and basal metabolic rate in nonalcoholic fatty liver disease by inhibiting the lipogenesis pathway in leptin receptor-deficient ob/ob mice." (PMID 31395940, 2019).
obesity syndromes (3 papers, 2021 to 2022). "In contrast to some monogenic obesity syndromes, which display classical Mendelian inheritance (LEP, LEPR, POMC and PCSK1), rare heterozygous variants in HTR2C are generally not fully penetrant." (PMID 36536256, 2022).
osteosarcoma (3 papers, 2021 to 2023). A usually aggressive malignant bone-forming mesenchymal neoplasm, predominantly affecting adolescents and young adults. "Moreso, aberrant alternative splicing of leptin receptor overlapping transcript (LEPROT) gene is also associated with osteosarcoma progression." (PMID 37755271, 2023). "Fifteen cases of primary osteosarcoma were analyzed for established markers associated with CAR cells (LEPR, EBF3, CXCL12, PDGFRA) and subdivided into low‐grade parosteal (7/16) or high‐grade intramedullary (9/16) tumors." (PMID 35309866, 2022). "EBF3 and LEPR followed the same expression pattern across low‐ and high‐grade tumors with nearly all LEPR+ osteosarcomas (6/8) also expressing EBF3." (PMID 35309866, 2022). "Here, we analyze osteosarcomas via immunohistochemistry for known markers of CAR cells such as leptin receptor (LEPR), B‐cell factor 3 (EBF3), CXCL12, and platelet‐derived growth factor receptor alpha (PDGFRA)." (PMID 35309866, 2022). "In this study, we show the abundant expression of the CAR cell–associated surface marker LEPR, and the characteristic transcription factor associated with CAR cells, EBF3, in a subset of human osteosarcoma samples." (PMID 35309866, 2022). "Immunohistochemistry for LEPR revealed a high propensity (8/9) for high‐grade osteosarcomas to be LEPR+, whereas low‐grade tumors displayed a lower rate of LEPR positivity (2/7) (p = 0.01) with signal predominantly and most intensely in tumor fibroblasts." (PMID 35309866, 2022). "In addition to enabling further clinical study of this LEPR+ subset of osteosarcoma, it should be noted that each of these cell types, including LEPR+ cells, have one or more cre lines that allow for conditionally targeting these cells in a murine preclinical model." (PMID 35309866, 2022).
ovarian tumors (3 papers, 2016 to 2023). "In addition, studies conducted on ovarian tumour explants indicated a worse prognosis among patients with a higher expression of the leptin receptor." (PMID 27480179, 2016).
overnutrition (3 papers, 2018 to 2020). An imbalanced nutritional status resulting from excessive intake of nutrients. "The decreased leptin sensitivity in the hypothalamic arcuate nucleus induced by early overnutrition is related to decreased expression of leptin receptor (LRb)." (PMID 32596284, 2020). "Our findings indicate that postnatal overnutrition led to significant age-dependent changes in synaptic transmission to ARH LepR-expressing cells." (PMID 32823489, 2020). "In agreement with former studies that indicated an influence of body weight on synaptic plasticity, we observed that postnatal overnutrition further increases the presynaptic excitatory transmission to ARH LepR-expressing cells, beyond the rise already observed with puberty." (PMID 32823489, 2020). "The excitatory transmission was further increased by postnatal overnutrition, whereas the amplitude of inhibitory currents to ARH LepR-expressing cells was reduced in SL mice, suggesting that postnatal overweight exerts potent effects on ARH neurons activity." (PMID 32823489, 2020).
periodontitis (3 papers, 2022 to 2023). An acute or chronic inflammatory process that affects the tissues that surround and support the teeth. "It has been reported that leptin and leptin receptor (LEPR) are expressed in healthy and inflamed gingival tissues, and elevated serum leptin concentration has been associated with increased chronic periodontitis." (PMID 35216099, 2022). "Notably, recent clinical studies have reported the presence of ILCs in gingiva from human periodontitis patients and leptin receptor-deficient mice, although their pathological contributions have not been fully elucidated." (PMID 38015204, 2023).
pneumonia (3 papers, 2013 to 2024). An acute, acute and chronic, or chronic inflammation focally or diffusely affecting the lung parenchyma, caused by an infection in one or both of the lungs (by bacteria, viruses, fungi, or mycoplasma.). "The majority of the children deficient for LEP or LEPR (55% and 38%, respectively) suffered from recurrent episodes of serious respiratory afflictions such as pneumonia and upper respiratory tract infections." (PMID 37659411, 2023).
pulmonary arterial hypertension (3 papers, 2017 to 2023). Pulmonary arterial hypertension (PAH) is a group of diseases characterized by mean pulmonary artery pressure >20 mmHg and elevated pulmonary arterial resistance leading to right heart failure. "Upregulation of the leptin-leptin receptor axis has been shown to contribute to the pathogenesis of pulmonary arterial hypertension in humans and to experimental hypoxia-induced pulmonary hypertension in rats." (PMID 28085954, 2017). "This suggests that leptin could play a role in modulating vasomotion directly through leptin receptor present on smooth muscle cells and therefore contribute to the progression of systemic and pulmonary hypertension in SHR." (PMID 28085954, 2017).
viral infection (3 papers, 2019 to 2025). "This study establishes a relationship opening new avenues to investigate the specific role of the leptin receptor pathway in shaping host responses to viral infection." (PMID 40125513, 2025). "Several studies on mouse models of viral infection addressed the role of LEPR and leptin in the pathogenesis of infectious diseases." (PMID 36589459, 2022). "Nevertheless, analyzing this dataset suggested that leptin and LEPR are neither important for immune response nor to the degree of sensitivity of chicken spleens to viral infection." (PMID 31514326, 2019).
amebiasis (2 papers, 2014 to 2018). A parasitic infectious disorder caused by amoebas. "In addition, our earlier work has demonstrated a dramatic association between the human Q223R LepR mutation and amebiasis, a common cause of diarrheal morbidity and mortality among children globally." (PMID 24743494, 2014).
bone metastasis (2 papers, 2020 to 2021). Transfer of a neoplasm from its primary site to bones. "In clinical data, the correlation of leptin and leptin receptor expression with bone metastasis was detected in pulmonary adenocarcinoma patients." (PMID 33799880, 2021). "Statistical analysis revealed that high leptin receptor expression was significantly associated with occurrence of bone metastasis and TNM stage compared to patients with low leptin receptor expression." (PMID 32836215, 2020). "CXCR4 expression was positively correlated with leptin receptor levels, and incidence of bone metastasis was higher (62.5%) in the CXCR4 high expression group than in the CXCR4 low expression group (28.12%)." (PMID 32836215, 2020).
Cachexia (2 papers, 2021 to 2022). Severe weight loss, wasting of muscle, loss of appetite, and general debility related to a chronic disease. "CKD-associated cachexia and PEW in rats were ameliorated by a leptin antagonist, or by blockade of the leptin receptor." (PMID 35369060, 2022). "Leptin receptor antagonism represents a novel therapeutic strategy for cachexia in patients with INC by attenuating adipose tissue browning and muscle wasting." (PMID 34440723, 2021). "In this aspect, leptin receptor antagonists, such as this PLA, could provide a novel and superior approach than clearance of circulating leptin for cachexia in INC." (PMID 34440723, 2021).
chronic myeloid leukemia (2 papers, 2011 to 2023). "As BCR-ABL positive chronic myeloid leukemia cells express leptin receptor (OB-R) and as we observed an increase of OB-R expression in PCMDS co-cultured with FLFCs, we evaluated whether fatty acids could affect the expression of OB-R after 24 hours of culture." (PMID 21991326, 2011). "Studies in a mouse model of myeloproliferative neoplasms such as chronic myeloid leukemia (CML) revealed that malignant cells transform osteoblast lineage cells (maybe including CAR/LepR+ cells) into inflammatory myelofibrotic cells, supporting malignant cells at the expense of normal hematopoiesis." (PMID 36805714, 2023).
Clear Cell Renal Cell Carcinoma (2 papers, 2020 to 2024). "In contrast, MSC-2 clusters derived from the bone marrow of patients with clear cell renal cell carcinoma metastases maintained the classic MSC markers NT5E and THY1 (CD90), but the expression of VCAM1, LEPR, and CXCL12 was reduced." (PMID 39156727, 2024). "The objective of this study was to use IHC to compare leptin and leptin receptor expressions in clear cell renal cell carcinomas (ccRCC) in non-obese and obese patients to determine the association between these proteins with the clinicopathological features and prognosis of ccRCC." (PMID 32802842, 2020).
colorectal tumor (2 papers, 2014 to 2023). "It is of interest that even obese mice demonstrated a significant inhibition of colorectal tumor cell growth when they were genetically-derived to be deficient in either leptin or leptin-receptor." (PMID 24465801, 2014). "The inhibition of leptin signaling by the leptin receptor antagonist Allo aca reduced NOTCH1, IL-1R, and ObRb mRNA levels in colorectal tumor tissues." (PMID 38152619, 2023).
esophageal reflux (2 papers, 2015 to 2019). "Measurement of serum leptin receptor level may be useful in clinical practice; it was indicated that frequency of esophageal reflux was significantly lower in SSc patients with elevated than in those with reduced level of serum leptin receptor (6.3% vs. 35.3%, respectively)." (PMID 30806766, 2019).
gastrointestinal infections (2 papers, 2015 to 2025). "In the same cohort, approximately 40% of children with leptin or leptin receptor deficiency developed gastrointestinal infections with severe diarrhea requiring hospitalization and 38–55% had recurrent respiratory infections including pneumonia." (PMID 40944251, 2025).
HELLP syndrome (2 papers, 2010 to 2012). A life-threatening condition that can potentially complicate pregnancy. "The frequency of the A allele was 77.0% in the HELLP syndrome group and 73.0% in the healthy pregnant controls in the case of LEPR c.326A>G (K109)." (PMID 20149225, 2010). "We decided to study four leptin receptor (LEPR) SNP polymorphisms in HELLP syndrome patients by using quantitative real-time PCR and melting curve analysis." (PMID 20149225, 2010). "We determined four coding polymorphisms in LEPR gene in HELLP syndrome patient by using quantitative real-time PCR and melting curve analysis method, first time according to our knowledge." (PMID 20149225, 2010). "We decided to determine the LEPR SNP polymorphism in HELLP syndrome and normal healthy subjects." (PMID 20149225, 2010). "Interesting finding was that in the case of LEPR c.326A>G (K109) the AG genotype was present twice more frequent in HELLP syndrome close to be statistically significant difference." (PMID 20149225, 2010). "There is a lack of information on the role of LEPR and its polymorphisms on the leptin levels in PE and HELLP syndrome." (PMID 20149225, 2010). "However the LEPR c.326A>G AG genotype was twice more frequent and the (AG AG GG AG) haplotype was three times more frequent in HELLP syndrome patients." (PMID 20149225, 2010). "There are only a few publications on the LEPR gene polymorphism in PE, according to our knowledge it has not been studied in HELLP syndrome." (PMID 20149225, 2010). "LEPR c.326A>G, LEPR c.668A>G, LEPR c.1968G>C and LEPR c.3024A>G allele, genotype and haplotype polymorphisms were not different in HELLP syndrome patients and normotensive healthy pregnants." (PMID 20149225, 2010). "Although certain LEPR haplotypes are more frequent in HELLP syndrome, we conclude that there is no compelling evidence that the four studied LEPR SNP polymorphisms associated with the development of HELLP syndrome." (PMID 20149225, 2010). "However, the LEPR polymorphism has not been studied in HELLP syndrome (hemolysis, elevated liver enzymes, and low, platelet count), in the disease which is considered as a severe complication of PE." (PMID 20149225, 2010). "However a difference was observed in the frequency of the LEPR c.326A>G AG genotype, which was almost twice as frequent in HELLP syndrome, while it was not statistically significant (40.0% vs. 24.0%; p = 0.089)." (PMID 20149225, 2010).
Hyperphagia (2 papers, 2021 to 2022). "Eating behavior in LEPR heterozygotes: Hyperphagia in LEPR wt/- was not described in the evaluated studies." (PMID 34448070, 2021).
influenza (2 papers, 2021 to 2023). An acute viral infection of the respiratory tract, occurring in isolated cases, in epidemics, or in pandemics; it is caused by serologically different strains of viruses (influenzaviruses) designated A, B, and C, has a 3-day incubation period, and usually lasts for 3 to 10 days. "This study aimed to elucidate the association of SNPs in LEP, LEPR, and PPARG with humoral immune response to influenza vaccine in the Chinese Han population." (PMID 34745208, 2021). "In this study, we aimed to investigate the potential association of leptin gene (LEP), leptin receptor gene (LEPR), and peroxisome proliferator activated receptor gamma gene (PPARG) polymorphisms with humoral immune response to influenza vaccine." (PMID 34745208, 2021). "The stratified analysis found that LEPR rs6673591 GA + AA genotype was related to low responsiveness to influenza vaccine in males (OR = 1.96, 95% CI = 1.05–3.67)." (PMID 34745208, 2021). "The stratified analysis found the gender difference in the association of LEPR and PPARG variants with immune response to influenza vaccine." (PMID 34745208, 2021). "Association of SNPs in LEPR and PPARG with influenza vaccine-induced humoral responses stratified by gender." (PMID 34745208, 2021). "Univariate and multivariate logistic regression analyses were used to explore the association of SNPs in LEP, LEPR, and PPARG with humoral immune response to influenza vaccine." (PMID 34745208, 2021). "To investigate the roles of LEP, LEPR, and PPARG in the humoral immune response to influenza vaccine, we conducted an association study to compare the genotypic frequencies of 11 tag SNPs in these genes between the two groups in the Chinese Han population." (PMID 34745208, 2021). "We found that LEPR rs6673591 GA + AA genotype was correlated with low responsiveness to influenza vaccine only in males (OR = 1.96, 95% CI = 1.05–3.67), and PPARG rs17793951 AG + GG genotype was associated with low responsiveness to influenza vaccine in females (OR = 3.28, 95% CI = 1.61–6.67)." (PMID 34745208, 2021). "The most significant result was that PPARG rs17793951 AG + GG genotype was associated with low responsiveness to influenza vaccine, and we also observed that LEPR rs6673591 GA + AA genotype was correlated with low responsiveness to influenza vaccine only in males by stratified analysis." (PMID 34745208, 2021). "Compared with the CGGAGGC haplotype composed of LEPR rs1327118, rs7602, rs1137101, rs1938489, rs6673591, rs1137100, and rs13306523, the CAAAAAC haplotype was positively correlated with immune response of influenza vaccine (OR = 0.34, 95% CI = 0.15–0.77)." (PMID 34745208, 2021). "Nevertheless, the association between SNPs in LEP, LEPR, and PPARG and influenza vaccine-induced immune response has not been revealed in the Chinese Han population." (PMID 34745208, 2021).
ischemic stroke (2 papers, 2017 to 2023). A stroke disorder caused by obstruction of blood flow to the brain, due to thrombotic (local blood clot formation) or embolic (due to a blood clot or other material traveling from another site) event. "Only one study was searched and included in the pooled analysis, and it concluded that the LEPR 109GG and 223GG genotype carriers were associated with a threefold increased risk of ischemic stroke." (PMID 28368354, 2017). "We identified the elevation of angiopoietin-2 and leptin receptor as potential novel biomarkers for early detection of ischemic stroke." (PMID 37533068, 2023). "More importantly, we have identified some novel biomarkers, including angiopoietin-2 (Angpt2) and leptin receptor (Lepr), for the detection of ischemic stroke." (PMID 37533068, 2023).